AGR2 (anterior gradient 2, protein disulphide isomerase family member)
Diseases named in the same sentence as AGR2 in open-access papers (continued):
Sharing a sentence is not in itself a finding about the gene and the disease.
adenocarcinoma (37 papers, 2010 to 2025). A common cancer characterized by the presence of malignant glandular cells. "The cancer-associated protein Anterior Gradient 2 (AGR2) has been described, predominantly in adenocarcinomas." (PMID 29937991, 2018). "The human adenocarcinoma-associated gene, AGR2 (anterior gradient 2), induces expression of amphiregulin through activation of YAP1 in PC." (PMID 27738325, 2016). "AGR2 (anterior gradient 2) is a well-known oncogenic promoter that is generally recognized as a secreted protein that is overexpressed in a variety of adenocarcinomas, including breast, prostate, pancreatic, gastrointestinal and urothelial tumors." (PMID 41200187, 2025). "Human adenocarcinoma-related gene AGR2 induces bidirectional regulatory protein expression through Hippo pathway coactivator YAP1." (PMID 36147635, 2022). "The AGR2 and AGR3 genes have been shown by numerous groups to be functionally associated with adenocarcinoma progression and metastasis." (PMID 35857928, 2022). "Up-regulation of AGR2 is another characteristic of differentiation upon introduction of PENK into adenocarcinoma cells." (PMID 34911496, 2021). "AGR2 has been shown to stimulate the expression of the EGF receptor (EGFR) ligand amphiregulin (AREG) in adenocarcinoma cells." (PMID 31434729, 2019). "The upregulation of anterior gradient 2 (AGR2) was of particular interest, as this protein has been shown to promote oncogenesis in adenocarcinomas of several tissues, including the lung." (PMID 31434729, 2019). "The activation of AREG by AGR2 has been shown to be dependent on the Hippo pathway effector protein YAP1 in human adenocarcinoma cell lines." (PMID 31434729, 2019). "Another gene in the signature, Agr2, is known as an adenocarcinoma antigen, which promotes cell migration and metastasis." (PMID 31752667, 2019). "In an IHC study on 60 adenocarcinoma (AdC) samples, AGR2 expression was shown to be between moderate and high in AdC cases." (PMID 31247903, 2019). "To this end, we used different adenocarcinoma cell lines depleted for AGR2 (A549-Sh-AGR2, H23-Sh-AGR2 and H1838-Sh-AGR2)." (PMID 27240165, 2016). "All the adenocarcinoma media tested were positive for AGR2 as shown for LuCaP 23.1, LuCaP 23.12, LuCaP 70CR, and LuCaP 35CR (CR = castration resistant)." (PMID 27283903, 2016). "Previous work established that adenocarcinoma cell lines from the lung and esophagus are dependent on AGR2, YAP1, and AREG to maintain the transformed phenotype." (PMID 27764193, 2016). "AGR2 is clearly a significant biomarker for human adenocarcinoma and a potential target for drug discovery." (PMID 27100463, 2016). "Anterior gradient 2 (AGR2) is an adenocarcinoma antigen with elevated expression in many solid tumor types including prostate, breast, pancreatic, gastro-intestinal, lung." (PMID 26894971, 2016). "A sister line LuCaP 145.2 was positive for AGR2 but at a lower level than those of the adenocarcinoma lines." (PMID 27283903, 2016). "That adenocarcinomas with areas of mucinous histologic patterns in our study had higher AGR2 levels on average fits with a role for AGR2 in mucin production." (PMID 26445321, 2015). "Anterior gradient 2 (AGR2) is expressed by many solid tumor types and is known as an adenocarcinoma antigen." (PMID 26445321, 2015). "AGR2 stimulates adenocarcinoma cell growth and supports the development of many features associated with malignant transformation." (PMID 22333441, 2012). "A recent study demonstrated that AGR2's growth promoting properties are achieved through its induction of AREG expression in adenocarcinoma cells." (PMID 22333441, 2012). "When we examined AGR2 expression for each array spot, the level of AGR2 expression was increased in PIN lesions as well as adenocarcinoma compared to BPH and morphologically normal adjacent tissue (P < 0.0001)." (PMID 21144054, 2010). "Since this discovery, many studies reported the high expression of AGR2 in adenocarcinomas." (PMID 34452625, 2021).
adenocarcinoma (continued). "The up-regulation of AGR2 in LuCaP 70CR showed that PENK could also affect gene expression of adenocarcinoma cells." (PMID 34911496, 2021). "Of note, PENK signaling increased expression of the adenocarcinoma antigen AGR2 (electropherogram)." (PMID 34911496, 2021). "AGR2 is a protein disulfide isomerase localized in the endoplasmic reticulum in normal cells but is upregulated in a variety of human adenocarcinomas, where it may also be present in secreted and cell-surface-bound forms." (PMID 31434729, 2019). "Furthermore, the overexpression of AGR2 in adenocarcinomas promoted growth and aggressiveness in an ER localization-dependent manner." (PMID 31247903, 2019). "Interestingly, within adenocarcinoma samples, there was a slight trend toward lower levels of AGR2 with increasing Gleason score." (PMID 21144054, 2010). "The models for the function of AGR2 propose a role in attenuating ER stress responses, or signalling from the ER to regulate gene expression, in particular the amphiregulin gene, which may be critical for mediating the action on cultured adenocarcinoma cells, and also the EGF receptor gene." (PMID 27100463, 2016). "AGR2 and AGR3 genes are localized on chromosome 7, side by side (7p21.1), and their protein products are both overexpressed and their localizations deregulated in many types of adenocarcinomas." (PMID 35857928, 2022). "The discovery of the anterior gradient proteins AGR2 and AGR3, which are highly related members belonging to the protein disulfide isomerase (PDI) family, attracted researchers’ attention due to their putative involvement in adenocarcinoma development." (PMID 34452625, 2021). "Other AGR2+ adenocarcinoma LuCaP media (not shown) as well as collagenase digestion media of metastasis samples obtained directly from donor autopsies produced the same result." (PMID 27283903, 2016). "Indeed, eAGR2 was detected in the extracellular medium of adenocarcinoma organoids (Sh-ctl), but not in adenocarcinoma organoids silenced for AGR2 (Sh-AGR2)." (PMID 27240165, 2016).
infection (9 papers, 2011 to 2025). The state of being infected such as from the introduction of a foreign agent such as serum, vaccine, antigenic substance or organism. "In order to quantify mucus metaplasia in whole lungs of control and Pou2f3-/- animals, we analyzed gene expression of goblet cell markers, Foxa3, Agr2, Muc5ac, and Muc5b, 51 days post infection." (PMID 36073526, 2022). "At MOI 1 or 5 for HRV-A16, we found that gene expression of SPDEF, FOXA3, and AGR2 were significantly increased in ALI-PBEC at 48 h post-infection." (PMID 32637364, 2020). "qPCR analysis demonstrated that for genes that were affected either by infection challenge (e.g. AGR2, G6PC, RETNLB) or diet (e.g. IL1R2, CD3G, ADH1C), gene expression levels of the microarray were verified." (PMID 21698235, 2011). "AGR2 was among the most upregulated genes following infection in the basal progenitor cluster." (PMID 40766562, 2025). "To address if the ectopic lung tuft cells and cytokines may perform a similar role, we stained for Agr2 (anterior gradient 2) as a cellular marker of goblet cells at 25 days after infection, a stage when goblet cells are robustly present." (PMID 36073526, 2022). "The expression patterns of genes related to the interaction between protein nutrition and secondary infection, such as GYG1 and AGR2 were similar to those observed by the microarray." (PMID 21698235, 2011). "AGR2 was significantly upregulated following infection in all other cell clusters except for the non-proliferative cluster, where it is significantly downregulated following infection." (PMID 40766562, 2025). "From the genes selected for validation, FOXP1 tended to be higher in parasitized rats offered the LP diet compared to the other infection-diet combinations, whereas expression data for two other candidate genes (GYG1 and AGR2) were not confirmed." (PMID 21698235, 2011).
ampulla of Vater (3 papers, 2014 to 2020). "Napsin‐A (NAPSA) and anterior gradient protein 2 homolog (AGR2) were identified as potential stage‐specific candidates for stage IA and stage IIIA lung ADC." (PMID 32536039, 2020).
autosomal recessive disease (1 paper, 2023). Autosomal recessive form of disease. "With our study, we provided Moderate or Strong level of evidence for GDR for 11 genes that were not listed in OMIM as having phenotype entity: FBRSL1, AGR2, ACBD6, C1orf127, PAN2, VPS50, KCTD3, NOTCH3 (for autosomal recessive disease), FAT1, NRAP, and SCLT1." (PMID 39669245, 2023).
CNS tumors (1 paper, 2019). "Using a meta-analysis approach, the identified signal transduction pathways modulated in the CNS tumors overexpressing AGR2 are shown." (PMID 31247903, 2019). "Moreover, novel associated pathways and clinically relevant deregulated genes in AGR2 high CNS tumors are identified using a meta-analysis approach." (PMID 31247903, 2019).
AGR2 also shares sentences with these, for which no sentence is quoted: endometrioid endometrial carcinoma (2 papers); gastric adenocarcinoma (2); ileitis (2); lung adenoma (2); mesothelioma (2); Obesity (2); prostate (2); Rectal prolapse (2); acute myeloid leukemia (1); adenocarcinoma of the cervix (1); adenoma (1); adenosquamous carcinoma (1); adrenocortical tumors (1); anaplastic carcinomas of the thyroid (1); bladder urothelial carcinoma (1); breast adenocarcinoma (1); cervical intraepithelial neoplasms (1); Clear Cell Ovarian Cancer (1); cyst (1); diabetic nephropathy (1); dysplasia (1); embryonal carcinoma (1); escherichia coli infection (1); Failure to thrive (1); focal segmental glomerulosclerosis (1); follicular carcinomas (1); gastrointestinal tumor (1); glomerulonephritis (1); gynecological cancer (1); hypertensive nephropathy (1).
A further 21 diseases each share a sentence with AGR2 in 1 paper.